GDF15 (growth differentiation factor 15)
Diseases named in the same sentence as GDF15 in open-access papers (continued):
Sharing a sentence is not in itself a finding about the gene and the disease.
malnutrition (continued). "We found a significant increase in serum GDF15 levels in AECOPD patients with malnutrition, which was negatively correlated with nutritional indicators such as BMI, MAC, CC, TP, ALB, and PNI, while demonstrating a positive correlation with the inflammatory marker CRP." (PMID 39050134, 2024). "It is possible that GDF15 may contribute to the development of malnutrition by activating signal transduction pathways and interacting with neurotrophic factors." (PMID 39050134, 2024). "Accordingly, we hypothesized that serum GDF15 might be used as a potential biomarker to detect malnutrition in patients with AECOPD." (PMID 39050134, 2024). "This indicated that GDF-15 was involved in malnutrition in patients with AECOPD." (PMID 39050134, 2024). "The serum GDF-15 level differentiated malnutrition/inflammation according to the MIS (p = 0.031)." (PMID 34247467, 2021). "Our study expands upon the existing literature on GDF-15 in HD patients with malnutrition." (PMID 34247467, 2021). "The MIS together with the GDF-15 level might be considered a combined marker of the malnutrition/inflammation status and a good predictor for mortality in HD patients especially in the early period of malnutrition/inflammation." (PMID 34247467, 2021). "Three studies analyzed GDF-15 and mortality in HD patients, and all reported that a high GDF-15 level was associated with a high risk of mortality; however, none analyzed the patients’ malnutrition/inflammation status." (PMID 34247467, 2021). "In CKD, malnutrition status may elevate GDF-15, complicating interpretation." (PMID 41597417, 2026). "However, it is still unknown whether serum GDF15 levels can be used to predict malnutrition in patients with AECOPD." (PMID 39050134, 2024). "Serum GDF15 levels could be used as a potential diagnostic biomarker for predicting malnutrition in patients with AECOPD, providing direction for future clinical evaluations of malnutrition." (PMID 39050134, 2024). "GDF-15 might be useful for the objective assessment of malnutrition risk during the early period of HD, irrespective of weight loss or prominent inflammation." (PMID 34247467, 2021). "GDF15 may contribute to malnutrition in patients with cirrhotic PBC." (PMID 33178828, 2020). "The predictive value of serum GDF15, albumin (ALB), and a combination of these was evaluated to identify malnutrition in patients with AECOPD using a receiver operating characteristic (ROC) curve." (PMID 39050134, 2024). "Predictive value of serum GDF15 levels, serum ALB levels and their combination in malnutrition patients with AECOPD." (PMID 39050134, 2024). "Some studies have examined the prognostic significance of GDF-15 in HD patients, but findings related to the correlation between GDF-15 and the severity of malnutrition/inflammation is inconsistent." (PMID 34247467, 2021). "According to our findings, serum GDF-15 level with MIS is stronger than PNI and CONUT to estimate malnutrition in our HD patients." (PMID 34247467, 2021). "The malnutrition indicator CONUT score was not significantly correlated with GDF15, but a correlation between a worse CONUT score and GDF15 increase was observed." (PMID 41016991, 2026). "In the future, we may be able to use this platform to detect serum biomarkers, such as GDF15 and ALB to identify malnutrition in patients with AECOPD to provide early nutritional therapy." (PMID 39050134, 2024). "The optimal cut-off value of serum GDF15 levels and serum ALB levels for predictive malnutrition in AECOOPD patients was 1,092.885 pg/mL and 36.15 g/L, respectively, with a sensitivity of 65.90 and 86.40%, respectively, as well as specificity of 89.80 and 65.00%, respectively." (PMID 39050134, 2024). "Mitokines (Humanin (HN), GDF15 and FGF21) are produced as a result of mitochondrial dysfunction and may have major roles in chronic inflammation, malnutrition and exercise capacity in people with COPD." (PMID 36243733, 2022).
malnutrition (continued). "AUROC curves for the ability of GDF-15 to predict malnutrition according to the PNI and CONUT score were not significant (AUROC: 0.428; 95% CI: 0.3390.517; p = 0.117 and AUC: 0.433; 95% CI: 0.3440.523; 0.149, respectively)." (PMID 34247467, 2021). "Using this indicator alone with serum GDF15 levels to assess malnutrition might result in false negative results because serum GDF-15 levels might increase with age." (PMID 39050134, 2024). "Therefore, when GDF15 levels are elevated in AECOPD patients with concurrent malnutrition, potential targeted anti-inflammatory interventions may improve malnutrition." (PMID 39050134, 2024). "In this study, we examined the levels of serum GDF15 in AECOPD patients with and without malnutrition and the differences between the two groups were compared." (PMID 39050134, 2024). "Serum GDF15 levels in patients with malnutrition and AECOPD were significantly higher than those in patients without malnutrition, whereas the serum ALB levels were significantly lower than those in patients without malnutrition (p < 0.001)." (PMID 39050134, 2024).
rheumatoid arthritis (15 papers, 2015 to 2026). A chronic, systemic autoimmune disorder characterized by inflammation in the synovial membranes and articular surfaces. "For example, levels of GDF-15 are notably higher in patients with rheumatoid arthritis, correlating with disease severity and cardiovascular risk, underscoring its role in inflammation and lipid metabolism." (PMID 39328401, 2024). "For example, higher concentrations of GDF-15 in the blood have been observed in individuals with rheumatoid arthritis, where its levels correlate positively with the disease’s intensity and progression, highlighting its potential as a diagnostic marker." (PMID 40722837, 2025). "One study demonstrated that individuals diagnosed with rheumatoid arthritis, a long-standing inflammatory condition, exhibited elevated concentrations of GDF-15 in their blood." (PMID 40722837, 2025). "Elevated GDF-15 levels have been observed in other inflammatory conditions, such as rheumatoid arthritis, psoriasis, and Behçet’s disease, with some studies demonstrating a correlation between serum GDF-15 levels and disease activity." (PMID 38668313, 2024). "Our finding aligns with several studies in rheumatoid arthritis (RA) patients, psoriasis patients, or Behçet’s disease (BD) patients, where elevated GDF-15 levels were reported." (PMID 38668313, 2024). "A prospective study involving 46 patients with rheumatoid arthritis compared to 36 matched healthy controls revealed that serum level of GDF15 was higher in rheumatoid arthritis patients as compared to the controls." (PMID 36140453, 2022). "Serum GDF-15 was significantly higher in rheumatoid arthritis patients and correlated with disease activity and subclinical atherosclerosis." (PMID 33201838, 2020). "Similarly, patients with rheumatoid arthritis had higher GDF15 levels, which also correlated with disease activity." (PMID 41303556, 2025). "GDF-15, a cytokine involved in inflammation and tissue damage response, has been extensively studied and found to be elevated in numerous conditions, including non-communicable diseases, rheumatoid arthritis, juvenile dermatomyositis, and cardiovascular diseases." (PMID 39328401, 2024).
Cirrhosis (14 papers, 2015 to 2026). A chronic disorder of the liver in which liver tissue becomes scarred and is partially replaced by regenerative nodules and fibrotic tissue resulting in loss of liver function. "We investigated GDF‐15 in cirrhosis, focusing on its association with disease‐driving pathomechanisms, platelet function, hepatic decompensation, and mortality." (PMID 41555670, 2026). "Thus, the impact of GDF‐15 on cardiovascular risk in the setting of cirrhosis remains to be fully elucidated." (PMID 41555670, 2026). "Interestingly, a recent report of an association of GDF15 in an Asian population confirmed the association with cirrhosis despite a slightly higher cut-off." (PMID 28301573, 2017). "Besides, serum GDF15 levels were negatively associated with cirrhosis incidence (p = 0.019)." (PMID 40677718, 2025). "In conclusion, this study highlights GDF‐15 as a promising and easily available blood‐based biomarker in patients with cirrhosis which reflects key disease‐driving pathomechanisms including fibrogenesis and bacterial translocation." (PMID 41555670, 2026). "GDF‐15 is a promising biomarker in cirrhosis that reflects disease‐driving pathomechanisms and independently predicts decompensation and mortality." (PMID 41555670, 2026). "In the current study of patients with cirrhosis, higher GDF‐15 levels primarily reflected ongoing liver scarring, inflammation, and bacterial translocation from the gut, and were linked to a higher risk of liver‐related complications and death." (PMID 41555670, 2026). "Studies on human liver biopsies from individuals with cirrhosis or MASH have shown increased GDF15 expression across almost all liver cell types." (PMID 40530451, 2025). "Elevated serum GDF15 levels have been observed in various conditions, including diabetes, metabolic syndrome, and anorexia, and liver diseases such as cirrhosis and non-alcoholic fatty liver disease." (PMID 40677718, 2025). "Compared with healthy controls (serum GDF15 levels of 0.31 ± 0.01 ng/mL), HCC patients showed significantly increased GDF15 levels (6.66 ± 0.67 ng/mL) and so did the patients with cirrhosis (6.51 ± 1.47 ng/mL)." (PMID 35264787, 2022). "In non-cirrhosis patients, GDF15 levels were higher in AIH (1914.0 ± 1327.2) than in HC (955.7 ± 502.7), HB (519.3 ± 197.5), and PBC (643.9 ± 247.0) (p < 0.0001)." (PMID 35610317, 2022). "The present study showed that serum GDF15 levels in PBC patients with decompensated cirrhosis were markedly increased." (PMID 33178828, 2020). "Serum GDF15 levels of PBC patients with compensated cirrhosis were also moderately higher than those of healthy controls, but significantly lower than those of PBC patients with decompensated cirrhosis." (PMID 33178828, 2020). "ROC curve analysis was used to define the optimal cut-off to determine the sensitivity and specificity of serum GDF15 for categorizing PBC patients with decompensated cirrhosis versus PBC patients with compensated cirrhosis." (PMID 33178828, 2020). "Illustrating the biological function of circulating GDF15 in cirrhosis will help promote its potential application in the diagnosis and targeted therapy of cirrhotic PBC patients." (PMID 33178828, 2020). "In asymptomatic carriers of HCV and HBV, concentrations of GDF-15 are intermediate (lower than in cancer and cirrhosis patients and higher than in healthy individuals)." (PMID 28430124, 2017). "However, the low number of malignancies during the observation period has to be considered and further studies are clearly required to elucidate carcinogenic effects of GDF‐15 in cirrhosis." (PMID 41555670, 2026). "Notably, evaluated serum GDF15 levels have been reported in patients with cirrhosis (mean ± SEM: 6.51 ± 1.47 ng/mL) and HCC (mean ± SEM: 6.66 ± 0.67 ng/mL)." (PMID 40677718, 2025).
Cirrhosis (continued). "Increased GDF15 levels are observed in both cirrhosis and HCC stages and these high levels at the cirrhotic stage may be ‘carried forward’ to the HCC stage that may contribute to the observed hepcidin downregulation in HCC." (PMID 35264787, 2022). "Moreover, serum levels of GDF15 were significantly higher in PBC patients with decompensated cirrhosis than in PBC patients with compensated cirrhosis (6679.31 ± 828.27 vs. 2784.04 ± 477.06 pg/mL; p < 0.001)." (PMID 33178828, 2020). "The results showed that the serum levels of GDF15 could be effectively used to differentiate patients with decompensated cirrhosis among cirrhotic PBC patients." (PMID 33178828, 2020). "The ROC curve comparing PBC patients with decompensated cirrhosis and PBC patients with compensated cirrhosis in the cohort suggested that GDF15 could differentiate decompensated LC with an AUROC of 0.956." (PMID 33178828, 2020). "However, there were no significant intergroup differences in the concentrations of GDF-15 in patients with different stages of cirrhosis." (PMID 28430124, 2017). "In this study, we showed evidence that the serum level of GDF15 was significantly elevated in the patients with HCC and cirrhosis." (PMID 25996938, 2015). "Among the patients with chronic HBV or HCV infection, serum GDF15 levels were also moderately higher than the healthy controls but significantly lower than those with HCC and cirrhosis." (PMID 25996938, 2015). "Even so, it appears promising to combine GDF15 with other biochemical markers and imaging methods to improve the diagnosis of HCC and cirrhosis." (PMID 25996938, 2015). "Further research and the clinical implementation of serum GDF15 measurement as a biomarker for HCC and cirrhosis are recommended." (PMID 25996938, 2015). "In addition, serum GDF15 levels were also significantly higher in patients with cirrhosis (1926.6 ± 1026.0 pg/dL) than in those without cirrhosis (1249.1 ± 1124.1 pg/dL) (p < 0.0001)." (PMID 35610317, 2022). "They reported that GDF-15 could not discriminate between significant fibrosis (≥F2) and cirrhosis (≥F4) in patients staged with fibro-scan only." (PMID 34777864, 2021). "However, the clinical relevance of the relationship between circulating GDF15 and end-stage liver diseases, such as in PBC patients with cirrhosis, has not been reported." (PMID 33178828, 2020).
liver cancer (14 papers, 2017 to 2026). An epithelial or non-epithelial malignant neoplasm that arises from the liver. "Aberrant expression of GDF15 has been reported in multiple malignances including liver cancer, and is associated with patient prognosis." (PMID 40677718, 2025). "In liver cancer, GDF15 produced by the cancer stem cells promotes their proliferation and metastatic power." (PMID 38201456, 2023). "The mitokines FGF21 and GDF15 are upregulated during UPRmt and their levels are positively correlated with liver cancer development, progression, and metastasis." (PMID 34440674, 2021). "Genetic ablation of GDF15 in animal models of liver cancer inhibits tumor formation, growth, and invasiveness." (PMID 34440674, 2021). "Clinical data showed GDF15 was overexpressed in liver cancer tissues and was positively related to pathological grading." (PMID 28199981, 2017). "Moreover, the primary method of GDF-15 expression detection testing (ELISA) used a different cut-off value in each study, particularly that the cut-off points were obviously higher in gastric and liver cancers than other malignancies." (PMID 30808336, 2019). "Promisingly, GDF15 could be considered as a potential therapeutic target in liver cancer." (PMID 28199981, 2017). "Growth differentiation factor 15 (GDF15) facilitated tumor immunosuppression via interaction with CD48 on Treg cells and downregulation of E3 ligase STUB1, leading to accumulation of FOXP3 protein in liver cancer." (PMID 36733484, 2023). "The pooled AUC of GDF-15 to rule out PC, EC, GC, and liver cancer were estimated to be 0.82, 0.84, 0.90, and 0.85, respectively." (PMID 30808336, 2019).
Nephropathy (14 papers, 2018 to 2026). A nonspecific term referring to disease or damage of the kidneys. "Higher GDF-15 was associated with neuropathy (odds ratio (OR) 1.985; 95% confidence interval (CI) 1.431-2.753) and nephropathy (OR 1.673; 95% CI 1.243-2.254) in unadjusted models." (PMID 42074710, 2026). "GDF15 was associated with nephropathy (p = 0.011) and PVD (p = 0.035), while FGF21 showed a strong association with nephropathy (p < 0.001)." (PMID 40629349, 2025). "Plasma IL-8, IL-10, IL-17, C-C motif chemokine ligand 20 (CCL20), TNF-α and GDF15 correlated with kidney damage assessed as the magnitude of proteinuria." (PMID 39188767, 2024). "This study aims to investigate plasma MMP-3 and GDF-15 as systemic biomarkers for diabetic neuropathy and nephropathy in T1D." (PMID 39000435, 2024). "In this study, the intention was to investigate the potential of MMP-3 and GDF-15 as biomarkers for neuropathy and nephropathy in T1D." (PMID 39000435, 2024). "In conclusion, elevated levels of GDF15 protein are a cellular response to ongoing kidney damage; therefore, this protein can serve as a marker." (PMID 38132468, 2023). "Under physiological conditions, only a simultaneous deletion of Stab1 together with its close homolog Stab2 results in glomelurofibrotic nephropathy possibly by impairing the clearance of profibrotic cytokine GDF-15 in the liver." (PMID 30349531, 2018). "Namely, the increased GDF15 serum concentrations, known originally as markers of mortality in patients with isolated cardiovascular problems, turned into useful indices of CV condition in patients with concomitant kidney damage." (PMID 40076962, 2025). "Additionally, LC treatment promoted macrophage polarization towards the anti-inflammatory phenotype, downregulated GDF-15 expression, upregulated Klotho expression, and ameliorated kidney damage." (PMID 40362229, 2025). "Additionally, plasma IL-8, CXCL9, TNF-α and GDF15 showed significant correlation with kidney damage assessed by decreased eGFR." (PMID 39188767, 2024). "The purpose of this study is to examine whether circulating MMP-3 and GDF-15 can be used as biomarkers for detecting and monitoring diabetic neuropathy and/or nephropathy in T1D." (PMID 39000435, 2024). "The cause of the kidney damage was likely the lack of clearance of the TGF-β family member growth differentiation factor 15 (GDF-15), a ligand common for both StabilinStabilin-1 and Stabilin-2, and the accumulation of extracellular matrix material within the glomeruli." (PMID 32429122, 2020). "Plasma GDF15 and TNF-α and urinary TWEAK and GDF15 most consistently correlated with more active disease or more kidney damage assessed as either higher anti-PLA2R titres, lower eGFR or higher proteinuria." (PMID 39188767, 2024). "Overall, plasma TNF-α and GDF15 and urinary TWEAK and GDF15 most consistently correlated with more active disease and kidney damage assessed as either higher anti-PLA2R titres, lower eGFR or higher proteinuria." (PMID 39188767, 2024). "Additionally, urinary IL-6, TWEAK and GDF15 correlated with kidney damage assessed by decreased eGFR, while urinary IL-17, IL-18, TWEAK and GDF15 correlated with kidney damage assessed as the magnitude of proteinuria." (PMID 39188767, 2024). "On the basis of those reports, it can be concluded that GDF15 can potentially be used as a marker of kidney damage and fibrosis, although its functions are not well understood." (PMID 38132468, 2023). "Importantly, the absence of GDF-15 worsens kidney damage, as GDF-15 helps reduce macrophage activation by inhibiting the NF-κB pathway." (PMID 40362229, 2025).